CD69 (CD69 molecule)
Diseases named in the same sentence as CD69 in open-access papers (continued):
Sharing a sentence is not in itself a finding about the gene and the disease.
infection (continued). "Polyfunctionality of these cells in regard to major Th1 cytokine production (MIP-1β, IFN-γ, IL-2) and expression of activation/proliferation markers, i.e., CD69, CD38, CD25, and Ki67, suggest a potential central role in the control of infection." (PMID 34283810, 2021). "Enadenotucirev infection also promoted IFN-γ release and CD69 expression, with only modest changes in CD107a." (PMID 32195317, 2020). "We also identify a number of host proteins that are upregulated by HIV during infection, including CCR7, CXCR5, and CD69." (PMID 32452381, 2020). "For example, following infection with Listeria monocytogenes (LM), splenic MPEC and SLEC lack expression of the TRM receptors, CD69 and CD103." (PMID 33815352, 2020). "Infection with STM-4/74 RibB++ induced low levels of cytokine production and CD69 expression by MAIT cells, recapitulating the phenotype of STM-D23580." (PMID 32788367, 2020). "The only consistently recognized CD4+ Trm cell marker is CD69, and the phenotypic characteristics of CD4+ Trm cells over the course of infection are unclear." (PMID 31815739, 2020). "Although CD69 expression was increased in DENV-infected children and predictive of infection, the NK cell phenotype was also characterized by CD57 expression." (PMID 33067399, 2020). "Upon infection with LOAd viruses, both CD4+ and CD8+ T cells were able to highly upregulate CD107a as well as the activation marker CD69 in co-culture with MM cells." (PMID 32355275, 2020). "IFNγ and CD69 mRNA expression, as well as the percentage of perforin-producing CD8+ T Lymphocytes, were analyzed 3 and 7-days post in vitro HIV-1-infection, respectively." (PMID 31379846, 2019). "Upon challenge infection, CD4+T cells constituted 7.4–12.6% of the total splenocytes, and a large proportion of the CD4+T cells exhibited a CD69+/CD11a+ phenotype (range: 7.7–22%) indicative of T cell recruitment and early activation." (PMID 31293599, 2019). "Assessment of the persistence of TRM cells in the respiratory tissue revealed a high number of CD69+CD4+ TRM cells in the lungs and nasal tissue 7 days after secondary infection with B. pertussis." (PMID 30866771, 2019). "Both CD8+ T cell populations trafficked into the skin on day 15 post-infection and previously naïve CD8+ T cells began expressing CD103 and CD69, but TCM CD8+ T cells in the same skin microenvironment expressed only CD69." (PMID 30875408, 2019). "In influenza infection, CD8 T cells in the tissue express CD49a, CD69, and CD103 by day 14, suggesting cells with a TRM phenotype develop relatively early as the tissue recovers from infection." (PMID 31635290, 2019). "As observed in vaccinees, YF-17D infection of PBMCs also induced upregulation of activation markers on various immune cells, including CD80 and CD86 on myeloid DCs (mDCs) and CD54 and CD69 on monocytes." (PMID 31285858, 2019). "Our results demonstrated that the percentages of MHC II-, CD69-, and NKG2A/C/E-expressing cells in TLR3+ NK cells increased significantly after infection (P < 0.05)." (PMID 30246036, 2018). "We therefore used intravascular staining to quantify M-specific and M2-specific TRM cells in the lung parenchyma based on expression of CD69 and CD103 after infection with RSV or vaccination with MCMV-M or MCMV-M2 alone or a combination of MCMV-M and MCMV-M2." (PMID 30154789, 2018). "Whereas the velogenic strains significantly downregulates the expression of CD69, B-Lec and IFN-γ of CD3−/28-4+ IEL-NK cells in chickens, infection with the lentogenic pathotype lead to the upregulation of the these receptors." (PMID 29973933, 2018). "The number and activation of F4/80+ macrophages, CD11b+CD11c+ dendritic cells (DCs) as well as CD4+CD25+ and CD8+CD69+ T lymphocytes were determined by flow cytometry in DT-treated and control DEREG mice at weeks 6 and 10 of infection." (PMID 30410119, 2018).
infection (continued). "Yet, interestingly, among all of the infants studied, there was a strong inverse correlation between the percentage of activated CD69+ CD4+ T cells in the peripheral blood at the time of the first challenge and the number of challenges to infection." (PMID 29359183, 2018). "We have recently reported that infection with Bordetella pertussis induces CD69+ CD4 TRM cells and a significant proportion of these cells stably express CD103 through the course of infection and after clearance of the bacteria." (PMID 30147701, 2018). "Eventually, the T cells at the site of initial infection upregulate CD103 and CD69 suggesting they assume the CD4+ TRM phenotype between 30 and 90 days post infection." (PMID 30038624, 2018). "Not only the percentages of MHC II-, CD69-, and NKG2A/C/E-expressing cells but also the percentages of IL-4-, IL-5-, and IL-17-producing cells in TLR3+ NK cells increased significantly after infection (P < 0.05)." (PMID 30246036, 2018). "CD69 and CCR5 were upregulated early after infection on CD4+ T cells in all three animals, and α4β7 expression also increased in DF98 over time despite an initial drop." (PMID 29259582, 2017). "During infection, CD8+ T cells in perigonadal fat expressed an effector phenotype (CD8+ CD44– CD69+) that was also seen in the lung where, in addition, CD4+ T cells with similar characteristics were identified." (PMID 29040326, 2017). "To measure the ability of GBS or S. suis to induce optimal activation of NK1.1+ cells, we measure surface expression of CD69 and the production of TNF-α, a cytokine described to be produced by these cells in the context of infection." (PMID 28706510, 2017). "This population significantly increases (p < 0.0001) over the course of infection, and at the late chronic stage (12 weeks postinfection), 38 ± 1% of CD8+ T cells were observed to be positive for CD103 and CD69." (PMID 28424687, 2017). "The majority of liver sporozoite-specific memory T cells expressed CD69, a phenotypic marker of tissue-resident memory (TRM) cells, which are well positioned to rapidly control liver-stage infection." (PMID 28182750, 2017). "The increase in frequency of CD69+CD8+ Teffs suggested the release and expansion of tissue-resident T cells following infection." (PMID 28815218, 2017). "Expression of the activation and effector function markers CD69, CD160, CD44, and CD62L were analyzed at day 6 post infection (p.i.)." (PMID 28261571, 2017). "CD4+ T cells were cultured in IL-2+ Ritonavir for single round infection, or additionally stimulated with PHA which resulted in a strong induction of activation measured by CD25 and CD69." (PMID 27383627, 2016). "More recently, in a S. pneumoniae mouse model of infection, CD4+ T cells exhibited significant upregulation of CD69 in the spleen." (PMID 26989699, 2016). "Expression of CD69, an early T cell activation marker, was significantly lower in draining MLN CD8+ T cells in Axl-/- mice in comparison to WT controls 3 days post-infection with PR8." (PMID 27350258, 2016). "In spleen, the frequency of CD69+ cNK cells was higher on those from RH- and ME49-infected animals compared with cps1-1, which may indicate higher level of activation-induced cell death and explain the loss of the mature cNK cell population in RH and ME49 infections." (PMID 27721814, 2016). "Infections were done with the WT or Vpr Δ HIV-1 GFP reporter viruses, so that gating on GFP+ cells allowed to specifically measure CD69 expression in HIV-1 infected cells." (PMID 27383627, 2016). "The percentages of expression of CD8, CD69, CD85j, NKG2D, NKp46, NKp44 and NKp30 were similar among dNK cells added just after or 16 h after infection." (PMID 27267272, 2016). "An analogous pattern of CD69 expression was seen in adult and old CD4+ T cells, although a smaller subset of cells was activated (e.g., 31% at 2 days after infection)." (PMID 26204259, 2015).
infection (continued). "Of specific note, after the infection with LCMV, the frequency of BM and spleen CD69+ cells decreased in the TEM subset, while the frequency of BM CD69+ cells in the TCM subset remained the same." (PMID 26793197, 2015). "To investigate this further, we examined a panel of T cell activation markers (CD62L, CD69, CD44, CD25) and homing receptors (CCR5, CXCR3, CCR7) at days 5, 6 and 7 post-infection." (PMID 24809749, 2014). "On day 6 post-infection, Socs4R108X/R108X (Thy1.2) CD8 T cells migrating to the lungs had significantly lower levels of CD69 expression than wild-type (Thy1.1) CD8 cells." (PMID 24809749, 2014). "There was variability in the effect of infection on both receptors among cell donors, but with a single exception, all infections produced significant CD62L down modulation and CD69 upregulation." (PMID 25330112, 2014). "Infection with SIV resulted in a significant increase in the proportion of CD69-expressing CD4+ T cells, beginning in primary infection (Mann-Whitney test, p = 0.042)." (PMID 24348253, 2013). "We compared the presence of MHC-II and two markers of T cell activation (CD69 and CD54) on transferred CD8 T cells in spleen, PLN and MLN as a function of time after intravenous infection with LCMV Arm." (PMID 23441229, 2013). "Other indicators of T cell activation such as the up-regulation of the early activation marker CD69 and the down-regulation of the lymph node homing molecule CD62L were also observed during the course of infection." (PMID 22912884, 2012). "In the course of infection, CD4+ T cells were collected and analyzed for the expression of early CD69 and late CD30 activation markers using flow cytometry." (PMID 22359669, 2012). "Using the simian immunodeficiency virus (SIV) rhesus macaque model, we compared expression of CD69 on T cells from the intestine, spleen, lymph nodes, and blood of normal and SIV-infected macaques throughout infection." (PMID 22096538, 2011). "Further, marked, selective depletion of intestinal CD4+CD69+ T cells occurred in early SIV infection, and this depletion persisted throughout infection." (PMID 22096538, 2011). "Surprisingly, the number of total or activated (CD69+) CD4+ T cells that were elicited to the lungs of RSV infected mice did not change when cDC and pDC or cDC alone were expanded before infection." (PMID 18320041, 2008). "At 3 days p.i., the number of infiltrating cells was greater after infection with vΔC16, and more CD4+ and CD8+ T cells were activated (CD69+)." (PMID 18796705, 2008). "In the absence of C16, the recruitment of inflammatory cells in the lung and bronchoalveolar lavage was increased early after infection (day 3) and more CD4+ and CD8+ T cells expressed the CD69 activation marker." (PMID 18796705, 2008). "The expression of CD69 and the capacity to lyse the NK cell-sensitive target cell YAC-1 were both increased over naïe and mock-infected controls as early as 6 h post-infection with HSV-1." (PMID 17407097, 2007). "Also, high levels of CD69+ CD4 T-cells persisted until the sixth and seventh months after infection in adult patients." (PMID 41011738, 2025). "Focusing on CD4 T cells, we could identify a reduced median signal intensity for CD69 in HPV–positive (focal) compared to HPV–negative samples, which suggests lower activation of these cells during the infection (cluster X, FC of 0.90 and p-adj of 0.04)." (PMID 39836629, 2025). "CD69, CD31 and ERG triple positive cells were detected in the lungs 7 days post infection (dpi)." (PMID 40617350, 2025). "Around half of CD4 T cells expressed both CD69 and CXCR6 beyond 4 weeks post infection." (PMID 40060443, 2025). "Prior to infection, we verified that CCL19-treated CD4 + T cells exhibited minimal expression of CD69 and CD25, confirming a resting phenotype, whereas cells treated with phytohaemagglutinin (PHA) and interleukin-2 (IL-2) for 24 hours showed robust upregulation of both markers." (PMID 40372991, 2025).
infection (continued). "However, after infection, CD103−CD8+ T cells were activated, with upregulated expression of CD69, ICOS, PD-1, and TIGIT (p < 0.05)." (PMID 41459157, 2025). "Additionally, the presence of mature, HBV-specific memory NK cells (mNKs) was demonstrated in humans exposed to HBV antigens through vaccination or infection, which was mediated by CD56dim NK cells co-expressing CD57, CD69 and KLRG1." (PMID 38793619, 2024). "Analysis of CD69 and CD103 expression in the lung pre- and post-Lpn challenge revealed a lack of tissue residency marker expression among CD4+ TIA cells prior to the Lpn infection." (PMID 38838013, 2024). "There was no discernible change in total CD4 T cells or any CD69+ cell populations over the course of infection." (PMID 39150988, 2024). "Furthermore, we found that even at the lowest ratio of 1:20, both exposed and infected MAIT cells demonstrated significantly lower levels of CD69 and IFN-γ co-expression compared to mock infection across all stimulation conditions." (PMID 39110717, 2024). "Similarly, we found increases in CD69+ frequencies of CD16-CD56high and CD16+CD56dim human NK cells upon PBMC infection with TVH." (PMID 36997583, 2023). "Patients with HM had a significant rise (P = .02) in the frequency of spike-specific activated CD134+CD137+CD4+ T cells post–BT infection but not spike-specific activated CD69+CD137+CD8+ T cells (P = .77)." (PMID 38023562, 2023). "Second, complementing the ΔVpr virus with Vpr in trans allowed for Vpr packaging into virions and delivery into cells without de novo Vpr synthesis during infection, and fully rescued upregulation of CD69 and CXCR6 spinoculation of resting CD4+ T cells." (PMID 35417711, 2022). "The HIV-p24+ subset was enriched for CD69+ cells, suggesting upregulation of CD69 following infection rather than preferential infection of CD69+ target cells." (PMID 34465136, 2022). "In contrast, CD69-expressing cells were maintained in the uninfected population, suggesting they were not preferentially targeted for infection." (PMID 34465136, 2022). "Furthermore, both CD8+ and CD4+ Ag-specific T cells in the BAL up-regulated markers of tissue residence, CD69 and CD103, between days 7 and 10 post-infection." (PMID 35271298, 2022). "Additionally, intravenous administration of BCG in NHPs provided robust protection against infection, and BCG IV vaccinated NHP had high levels of CD69 + Trm in lungs in contrast to intradermal or aerosol BCG vaccinated NHP37." (PMID 36456599, 2022). "Moreover, splenic primary memory OT‐I cells (those maintained after one infection) and tertiary memory OT‐I cells (those maintained after three infections) exhibited similar phenotypes, based upon CD44, CD127, CD69, CD103 and GrB expression." (PMID 34407221, 2021). "In our study, increased expression of CD69, ICOS, and PD-1, and the decreased expression of CD62L on the surface of infection induced splenic γδT cells demonstrating that P. yoelii NSM infection could induce γδT cell activation." (PMID 35127555, 2021). "During the early stage of infection, 40–50% of brain CD8 T cells were CD69+CD103-." (PMID 34587172, 2021). "Stable populations of Tmem cells remain present in the peripheral organs after the clearance of an infection due to KLF2 downregulation, leading to an active form of CD69 which blocks S1PR1 function by conformational changes due to CD69/S1PR1 binding and an inhibition of S1PR1 expression." (PMID 34696279, 2021). "In addition, the expression of IFN-γ, TNF-α, CD69, and IFN-γ mRNA in the lung CD4+ T cells and IFN-γ in spleen CD4+ T cells significantly elevated after infection in WT mice (p = 0.00012, 0.0172, 0.0038, 0.00562, and 0.0117, respectively)." (PMID 33628846, 2021). "At all doses of MCMV, splenic NK cell activation was observed on day 1.5 post-infection (pi) as indicated by CD69 expression, an activation marker not expressed on naïve NK cells, and concomitant with increased HIF1α expression." (PMID 34396954, 2021).
infection (continued). "Thus, the rapid and widespread induction of CD69 on immune cells upon infection and inflammation makes specific targeting of TRM cells via CD69 challenging." (PMID 33467606, 2021). "Also, the higher the levels of HIV-1 viral load, the more CD69-expressing TIGIT+NK cells and TIGIT−NK cells were detected at the acute stage of infection (TIGIT+NK: r = 0.33, P = 0.052; TIGIT−NK: r = −0.53, P = 0.001)." (PMID 33717085, 2021). "At 22–30 days post-infection, IV exclusion was performed and negatively enriched pooled groups of spleens (3–5 spleens/sample, n = 3) or mLNs (15–25 mLNs/sample, n = 2) were stained for CD8α, CD90.1, CD69, and CD103." (PMID 34143731, 2021). "In contrast to conventional CD8+ T cells, MAIT cells are CD44hi, CD62Llo and express CD69 in naive mice, and the expression of these markers did not change following infection." (PMID 34272362, 2021). "The data also showed that MAIT cells expressed more CD69 (gut aGVHD vs. no-event, p = 0.02; gut aGVHD vs. infection or fever, p = 0.011), CXCR3, and CXCR4 in the gut aGVHD group than in the other two groups." (PMID 34539656, 2021). "After clearance of the infection, a pool of these cells settled in the GT as tissue-resident Th1 and Th17 cells expressing CD69 but not CD103, CD49d, or CCR7, where they responded rapidly to a reinfection." (PMID 31993218, 2020). "In the spleen, P. berghei K173 infection induced a global activation of lymphocytes and DC, as exemplified by the upregulation of CD69 on T cells, B cells, and NK cells (not shown), and of CD86 on DC." (PMID 32265335, 2020). "At the same time point post-infection, we also found that expression of the activation marker CD69 was upregulated on CD4+ T cells in the lungs of WT but not Il17a-KO mice." (PMID 32636457, 2020). "CD69 mRNA expression (a marker of early T cell activation) in IAV-infected pregnant aortas was up-regulated during the early phase (3 dpi) and persisted during the later phases (6 dpi) of infection." (PMID 32958663, 2020). "The results revealed that CD69+ TRM cells were still present in the respiratory tract, especially the nasal tissue, following clearance of a primary infection with B. pertussis; these cells expanded dramatically 7 days after re-infection." (PMID 30866771, 2019). "We thereby measured CD69 expression directly in patient blood samples, without re-stimulation, remaining close to the induced in vivo phenotype of an early natural infection." (PMID 31921133, 2019). "The greatest number of IL-17 or IFN-γ-secreting CD69+CD4+ TRM cells in the lungs and nose 7 days post challenge was induced by previous infection, followed by wP-immunization, while immunization with an aP vaccine did not induce cytokine production above control level." (PMID 30866771, 2019). "Indeed we have already reported that CD69+CD4+ TRM cells accumulate in the lungs during infection with B. pertussis, expand after re-infection and promote clearance of the secondary infection." (PMID 30866771, 2019). "To determine whether adoptive transfer of cells to naïve mice enhanced the Th1 and Th17 responses in the lungs after infection, we assessed IFN-γ and IL-17 production by ICS and flow cytometry on lung CD69+CD4+ TRM cells 13 days post challenge." (PMID 30866771, 2019). "Finally, on day 40 post-infection, the naïve CD8+ T cells formed mature CD69+/CD103+ TRM CD8+ T cells, but the TCM remained largely CD69+/CD103-." (PMID 30875408, 2019). "To determine which of these subsets differentiated into CD69+ TRM that formed in the skin, we sorted TCM and TEM P14 CD8+ T cells based on expression of CD62L and transferred equal numbers into naïve mice followed by infection with VacV-GP33." (PMID 30875408, 2019). "We observed that, although most NKT cells were negative for CD69 in uninfected mice (day 0), the number of CD69+ NKT cells peaked 3 days after infection, indicating that activated NKT cells accumulated early after viral challenge." (PMID 29249358, 2018).